RNU6-1283P (RNA, U6 small nuclear 1283, pseudogene)
Gene: Small nuclear RNA gene on chromosome 1 (246,189,014 to 246,189,118, reverse strand). Ensembl gene ENSG00000202184.
Homologues: Orthologues: chimpanzee U6 (100% identical), macaque U6 (95% identical), dog U6 (74% identical). Paralogues in human: RNU6-1060P (89% identical), RNU6-19P (87% identical), RNU6-41P (87% identical), RNU6-116P (86% identical), RNU6-348P (86% identical), RNU6-378P (86% identical), RNU6-46P (86% identical), RNU6-748P (86% identical), RNU6-820P (86% identical), RNU6-891P (86% identical), RNU6-1019P (85% identical), RNU6-1075P (85% identical), and 1287 more.